BCL7C (BAF chromatin remodeling complex subunit BCL7C)
Description:
May play an anti-apoptotic role.
Synonyms: SMARCJ3
Tractability: PROTAC: its protein half-life has been measured.
Gene: Protein-coding gene on chromosome 16 (30,833,626 to 30,894,302, reverse strand). Ensembl gene ENSG00000099385.
Subcellular location (Human Protein Atlas): Nucleoplasm
Pathways (Reactome):
Chromatin organization: Formation of neuronal progenitor and neuronal BAF (npBAF and nBAF); Formation of the canonical BAF (cBAF) complex; Formation of the embryonic stem cell BAF (esBAF) complex; Formation of the non-canonical BAF (ncBAF) complex; Formation of the polybromo-BAF (pBAF) complex
Developmental Biology: Regulation of MITF-M-dependent genes involved in pigmentation
Gene expression (Transcription): Regulation of endogenous retroelements by Piwi-interacting RNAs (piRNAs)
Gene Ontology:
Molecular function: protein binding
Biological process: chromatin remodeling; negative regulation of cell differentiation; positive regulation of cell population proliferation; positive regulation of double-strand break repair; positive regulation of stem cell population maintenance; regulation of G0 to G1 transition; regulation of G1/S transition of mitotic cell cycle; regulation of mitotic metaphase/anaphase transition; regulation of nucleotide-excision repair; regulation of transcription by RNA polymerase II
Cellular component: SWI/SNF complex; chromatin; GBAF complex; nucleoplasm
Genetic constraint (gnomAD): Loss-of-function variants: 8 observed, 26.43 expected, observed/expected ratio (o/e) 0.3, 90% interval 0.18 to 0.55. The upper end of that interval is the gene's LOEUF score, 0.55, which puts it in group 2 of 6, group 1 being the genes least tolerant of losing a copy. Missense variants: 262 observed, 298.35 expected, observed/expected ratio (o/e) 0.88, 90% interval 0.79 to 0.97. Synonymous variants: 90 observed, 115.14 expected, observed/expected ratio (o/e) 0.78, 90% interval 0.66 to 0.93.
Homologues: Orthologues: pig BCL7C (98% identical), mouse Bcl7c (93% identical), chimpanzee BCL7C (85% identical), macaque BCL7C (85% identical), dog BCL7C (83% identical), rat Bcl7c (79% identical), guinea pig BCL7C (53% identical), tropical clawed frog bcl7c (45% identical), Drosophila melanogaster BCL7-like (21% identical), Caenorhabditis elegans bcl-7 (20% identical). Paralogues in human: BCL7B (46% identical), BCL7A (35% identical).
Diseases named in the same sentence as BCL7C in open-access papers:
BCL7C is named in the same sentence as 14 diseases in open-access papers, as found by Europe PMC text mining. Sharing a sentence is not in itself a finding about the gene and the disease. The quoted sentences say what the papers report.
atrophic gastritis (1 paper, 2025). "We also identified several upregulated genes involved in the cell cycle G1/S phase transition in mucous neck cells, including SMARCC2, BCL7C, and CDKN1A, indicating that mucous neck cells acquired an aberrant cell proliferation phenotype in the atrophic gastritis stage." (PMID 39905493, 2025).
brain cancer (1 paper, 2023). A primary or metastatic malignant neoplasm affecting the brain. "This is a gene-rich region and we also identified GWS gene associations at this locus with FBXL19, BCL7C and CTF1, all three genes being reasonable candidates with putative roles in neuronal development, neuronal degeneration and/or brain cancer." (PMID 36940203, 2023).
breast carcinoma (1 paper, 2025). "SMARCD2, BCL7C and SS18L1 are amplified in 6%–8% of breast cancer patients from the TCGA and METABRIC breast cancer patient cohorts." (PMID 41278204, 2025).
cognitive decline (1 paper, 2025). "SNPs in this region mapped to PRR14, SRCAP, and BCL7C—genes linked to brain function, neurodegeneration, and cognitive decline." (PMID 40332088, 2025). "The association of BCL7C with neurodegeneration and cognitive decline is less well characterized, but it resides within the 16p11 locus, which has been associated with multi-traits genome-wide analysis (MTAG) studies of PD, DLB, and AD." (PMID 40332088, 2025).
glioma (1 paper, 2021). A benign or malignant brain and spinal cord tumor that arises from glial cells (astrocytes, oligodendrocytes, ependymal cells). "Remarkably, there was evidence that BCL7C expression was highly elevated in glioma in 6 out of 8 public datasets." (PMID 34362400, 2021). "Results from immunohistochemical (IHC) staining and public dataset validation demonstrated that BCL7B and BCL7C were highly expressed in glioma tissues compared to NBT." (PMID 34362400, 2021). "We found low BCL7A expression in 12 of 16 studies and high BCL7C expression in 11 of 12 studies in brain and CNS cancer." (PMID 34362400, 2021). "BCL7B and BCL7C were not independent risk factors for poor prognosis in all-gliomas patients in TCGA and CGGA datasets (respectively)." (PMID 34362400, 2021). "Also, BCL7C expression was higher in GBM compared to grade II–III glioma tissues in CGGA and TCGA." (PMID 34362400, 2021). "Notably, the expression of BCL7A and BCL7C was significantly lower and higher in glioma tissues, respectively, compared to non-tumor brain tissues (NBT)." (PMID 34362400, 2021).
lymphoma (1 paper, 2026). A malignant (clonal) proliferation of B- lymphocytes or T- lymphocytes which involves the lymph nodes, bone marrow and/or extranodal sites. "Initially identified through chromosomal translocations in lymphomas, the BCL7 protein family, comprising the three paralogues BCL7A, BCL7B, and BCL7C, has recently emerged as a core component of mammalian SWI/SNF ATP-dependent chromatin remodeling complexes." (PMID 42305078, 2026).
ovarian carcinoma (1 paper, 2023). A malignant neoplasm originating from the surface ovarian epithelium.
prostatic cancer (1 paper, 2019). "Hypermethylation of RASGRF2 has been associated with recurrence of prostatic cancer; BCL7B is a member of the BCL7 gene family (along with the genes BCL7A and BCL7C), in humans, the decrease in BCL7A expression is associated with development of NHL and epithelial lymphoma." (PMID 30908498, 2019).
cancer (5 papers, 2013 to 2023). A tumor composed of atypical neoplastic, often pleomorphic cells that invade other tissues. "Much less has been described in relation to BCL7B and BCL7C function in normal or cancer biology." (PMID 36801810, 2023).
tumor (4 papers, 2013 to 2023). "Both BCL7C and EML2 have similar functions as tumor suppressors, and both are related to islet β cells." (PMID 37894908, 2023). "PAPPA differs from BCL7C and EML2; its overexpression promotes tumor growth, and it is related to IGFBP hydrolysis and activation of NF-κB, PI3K, and other pathways, which are closely related to hair follicles and wool fibers." (PMID 37894908, 2023).
BCL7C also shares sentences with these, for which no sentence is quoted: B-cell lymphoma (1 paper); follicular thyroid adenoma (1); follicular thyroid carcinoma (1); medulloblastoma (1).